RNU6-228P (RNA, U6 small nuclear 228, pseudogene)
Gene: Small nuclear RNA gene on chromosome 20 (14,352,320 to 14,352,425, forward strand). Ensembl gene ENSG00000199570.
Homologues: Orthologues: chimpanzee U6 (93% identical), macaque U6 (88% identical), pig U6 (87% identical), dog U6 (82% identical), rat LOC120093910 (81% identical). Paralogues in human: RNU6-11P (91% identical), RNU6-37P (91% identical), RNU6-812P (91% identical), RNU6-1 (89% identical), RNU6-15P (89% identical), RNU6-2 (89% identical), RNU6-25P (89% identical), RNU6-3P (89% identical), RNU6-41P (89% identical), RNU6-4P (89% identical), RNU6-5P (89% identical), RNU6-6P (89% identical), and 1288 more.